MIR760 (microRNA 760)
Synonyms: hsa-mir-760; MIRN760; mir-760
Gene: MicroRNA gene on chromosome 1 (93,846,832 to 93,846,911, forward strand). Ensembl gene ENSG00000211575.
Gene Ontology:
Biological process: miRNA-mediated post-transcriptional gene silencing
Homologues: Orthologues: chimpanzee ptr-mir-760 (100% identical), rabbit MIR760 (100% identical), macaque MIR760 (89% identical), guinea pig MIR760 (84% identical).